DDIT4 (DNA damage inducible transcript 4)
Diseases named in the same sentence as DDIT4 in open-access papers (continued):
Sharing a sentence is not in itself a finding about the gene and the disease.
cancer (continued). "Currently, it is unknown if DDIT4 mitochondrial sequestration and biogenesis are a generalized feature of most cancer cell types, and it is likewise unknown how 1,25(OH)2D can regulate DDIT4 organellar sequestration and functional outcomes in those cancer cell types." (PMID 35079680, 2022). "Thus, it seems that Ddit4 played a unique and pivotal role in cancer cachexia." (PMID 34175899, 2021). "Therefore, there is a need to increase the knowledge regarding the role of DDIT4 in cell proliferation pathways and progression of cancer that may lead to improvement of prognosis and developing agents for targeted treatment." (PMID 34211002, 2021). "Several works have shown that DDIT4 may play a key role in cancer as an oncogene." (PMID 34659532, 2021). "Notably, recent studies highlighted the important roles of DDIT4 in various types of human cancer." (PMID 29976242, 2018). "Although mTOR pathway inhibition is a current targeted therapy strategy, several in vitro and in vivo studies have shown that DDIT4 expression could lead to cancer progression, resistance to treatment and angiogenesis, raising an important question about the mTOR biology." (PMID 28484222, 2017). "Inhibition of DDIT4 could be a good strategy in cancer treatment." (PMID 28484222, 2017). "Based on our results in U2OS cells and our analysis of cancer transcriptomes, it is likely that reduced PML expression observed in these cancers is correlated with reduced DDIT4 expression, which in turn could promote mTOR activation and promote cancer cell growth." (PMID 28332630, 2017). "In addition elucidation of DDIT4 participation in cancer aggressiveness could lead to improve the therapeutic strategies, mainly those related with mTOR inhibition." (PMID 27294413, 2016). "Previous studies have shown that baicalein induces the expression of DDIT4 and IRF-1 (Interferon regulatory factor-1), leading to inhibition of mTOR signaling in other cancer types." (PMID 41303544, 2025). "DNA damage inducible transcript 4 (DDIT4), expressed under stress situation, also acts as a mediator of cell growth in cancer cells through inhibition of mTORC1." (PMID 37016335, 2023). "After detection of CSC features, the RNA expression levels of DDIT4, SULF1, TPTEP1 and miRNAs (miR-181d-5p and miR-148b-3p) were measured using RT‐qPCR in colorectal CSC-enriched spheroids and HT-29 cancer cells." (PMID 34107956, 2021). "Among the identified DEGs, 5 candidate cancer-induced genes including BHLHE40, AREG, SOCS1, CCL5 and DDIT4 were selected for external validation on an independent set of PBMC samples of patients with various stages of HCC." (PMID 34045534, 2021). "Then, accurate scrutiny of hub genes҆ pathways displayed those 3 hub genes (MET, DDIT4, and SERPINB5) were involved in ‘microRNAs in cancer’ pathway, a part of pathways in CRC diseases based on KEGG database." (PMID 34211002, 2021). "Analysis of publicly available cancer data also revealed a significant correlation between PML and DDIT4 expression in several cancer types (e.g. lung, breast, prostate)." (PMID 28332630, 2017). "The HDAC6 inhibitor tubacin has been shown to promote cell death through the intrinsic apoptotic pathway by inducing the expression of cellular stress genes such as DDIT4 (RTP801/Dig2/REDD1) and DDIT3 (CHOP/GADD153), thereby triggering DNA damage in various cancer cells." (PMID 40843669, 2025). "Notably, HDAC6 inhibition activates DNA damage repair pathways by upregulating cellular stress genes such as DDIT4 (RTP801/Dig2/REDD1) and DDIT3 (CHOP/GADD153), highlighting its potential as a therapeutic target in cancer treatment." (PMID 40843669, 2025). "As reduced anabolic signalling also contributes to muscle atrophy in cancer cachexia, we tested the impact of AdipoRon on REDD‐1 expression (Ddit4), an inhibitor of the mammalian target of rapamycin complex 1 (mTORC1), which is under the positive transcriptional control of glucocorticoids." (PMID 38572511, 2024).
cancer (continued). "Immunofluorescence (IF) and fluorescence in situ hybridization (FISH) showed that S. pneumoniae was enriched in LUAD tissues, and DDIT4 expression was significantly higher in cancer tissues than in non-cancerous tissues." (PMID 36601406, 2022). "Similarly, we observed overexpression of some critical cancer related and regulatory genes such as GADD34, DDIT4, BNIP3, BNIP3L, NOXA, and LC3B-II in response to AQ treatments confirming the role of AQ in regulating the autophagy and cancer regulatory genes." (PMID 36232751, 2022). "Despite such limitations, our data demonstrated that circulating BHLHE40 and DDIT4 were differentially expressed in patients with HCC compared to individuals without cancer." (PMID 34045534, 2021). "In addition, in cancer cells, ER stress-induced activation of ATF4 downstream of eIF2α phosphorylation was reported to promote autophagy by activating DDIT4, which in turn increases eEF2K activity through mTOR inhibition." (PMID 32059483, 2020). "There are not previous reports relating DDIT4 with prognosis of cancer patients." (PMID 27294413, 2016). "Analysis with data from the Cell Miner Tool in 60 cancer cell lines indicated that although rapamycin activity was correlated with levels of MTOR, it is not influenced by DDIT4 expression." (PMID 28484222, 2017).
infection (13 papers, 2017 to 2025). The state of being infected such as from the introduction of a foreign agent such as serum, vaccine, antigenic substance or organism. "Repair of virus-induced DNA damage is critical for cell survival from IAV infection, and several DNA damage response-associated genes (Bub1, Ddit4, Pml) were found to be infection-specific." (PMID 32790753, 2020). "Among the 138 cellular mRNAs that exhibit reduced polysome association following infection was DNA-damage inducible transcript 4 (DDIT4) which encodes regulated in development and DNA-damage response 1 (Redd1)." (PMID 31226162, 2019). "For S. aureus infection, WSB1 (ubiquitination-related) was downregulated in S1, while only DDIT4 was downregulated in S3, suggesting broader impacts on stress pathways at higher infection concentrations." (PMID 40771952, 2025). "Infection of HeLa cells overexpressing DDIT4 resulted in a 60% reduction in the production of infectious VV particles compared with control HeLa cells expressing GFP." (PMID 33075093, 2020). "Inversely, infection of mouse embryonic fibroblast (MEF) cells obtained from DDIT4 knock out mice resulted in a six-fold increase in the production of infectious VV particles compared with MEF isolated from wild-type mice." (PMID 33075093, 2020). "Depletion of DDIT4/Redd1 by siRNA increased viral gene expression as evidenced from infection of cells with VSV-eGFP, and by metabolic labeling of viral protein synthesis." (PMID 31226162, 2019). "DDIT4 knockout markedly suppressed E. coli-induced pro-inflammatory IL-1β and TNF-α expression, as well as infection-induced NF-κB p65 phosphorylation and nuclear translocation." (PMID 34985734, 2022). "The expression levels of IFITM3, ZFP313, DDIT4, and CD47 were rapidly upregulated in the early stage of infection, though not very highly." (PMID 33614762, 2021). "We found that DDIT4, CTH, RELB, and SLC7A11, but not NDRG1 and CHAC1, increased in gastric tissues at 4 months post-infection (MPI)." (PMID 32457731, 2020).
neurodegenerative disease (10 papers, 2018 to 2025). A disorder of the central nervous system characterized by gradual and progressive loss of neural tissue and neurologic function. "KEGG pathway analysis implicated neurodegenerative diseases pathways and highlighted target genes associated with long-term depression signaling and tryptophan metabolism, including RIN2, TCF7L1, DDIT4, and KLF11." (PMID 41009397, 2025).
metabolic disorders (7 papers, 2016 to 2025). "Other scholars suggested that DDIT4 was strongly connected to metabolic disorder changes and metabolic functions, including its potential contribution to mitochondrial biology." (PMID 35692841, 2022).
bacterial infection (2 papers, 2025). "DDIT4 (DNA damage/stress regulator) consistently appeared across multiple groups (E, E1-E3, ES, S, S1-S3), potentially indicating bacterial infection-induced cellular stress or metabolic suppression." (PMID 40771952, 2025).
adenocarcinoma (1 paper, 2021). A common cancer characterized by the presence of malignant glandular cells. "The underlying mechanism of high DDIT4 expression in poorly differentiated adenocarcinoma may be related to mutation." (PMID 34007269, 2021).
cardiovascular disease (1 paper, 2024). "Additionally, several Dox_H3K27ac-upregulated genes including Egr-1, Adam17, Dusp6, Ddit4 and Angptl4 might potentially contribute to Dox-induced cardiotoxicity, since they have been proved to be associated with the progression of cardiovascular disease." (PMID 39014511, 2024).
hematologic malignancies (1 paper, 2021). "A recent in silico analysis demonstrated that high levels of DDIT4 were significantly associated with poor prognosis of hematologic malignancies and several solid tumors, such as breast, colon and lung cancers." (PMID 34045534, 2021).
DDIT4 also shares sentences with these, for which no sentence is quoted: Insulin resistance (8 papers); Hyperglycemia (6); lymphoma (5); skin atrophy (5); muscle atrophy (4); Anxiety (3); cardiomyopathy (3); cognitive deficits (3); Huntington disease (3); inflammation (3); myeloid leukemia (3); neurological diseases (3); serous adenocarcinoma (3); Skeletal muscle atrophy (3); type 2 diabetes (3); age-related macular degeneration (2); Cerebral ischemia (2); COVID-19 (2); diabetic macular edema (2); endothelial dysfunction (2); gout (2); head and neck carcinoma (2); Hepatic steatosis (2); hepatocellular carcinoma (2); Hyperammonemia (2); Hypertension (2); iron deficiency (2); kidney (2); Lewis lung carcinoma (2); lymph node metastasis (2).
A further 70 diseases each share a sentence with DDIT4 in 2 papers or fewer.